UNC80 (unc-80 subunit of NALCN channel complex)
Description:
Auxilary subunit of the NALCN channelosome complex, which regulates the resting membrane potential by depolarizing sodium leak currents. The NALCN channelosome complex is a voltage-gated ion channel responsible for the resting Na(+) permeability that controls neuronal excitability. The NALCN channelosome is constitutively active and conducts monovalent cations but is blocked by physiological concentrations of extracellular divalent cations. Activated by neuropeptides substance P, neurotensin, and extracellular Ca(2+) that regulates neuronal excitability by controlling the sizes of NALCN-dependent sodium-leak current. UNC80 is also essential for NALCN sensitivity to extracellular Ca(2+).
Synonyms: C2orf21; KIAA1843; FLJ33496; UNC-80
Tractability: Small molecule: a structure with a bound ligand is known. Antibody: UniProt places it where antibodies can reach, with high confidence; its Gene Ontology location is reachable by antibodies, with high confidence; UniProt predicts a signal peptide or a membrane-spanning region. PROTAC: ubiquitination databases record sites on it.
Gene: Protein-coding gene on chromosome 2 (209,771,569 to 209,999,300, forward strand). Ensembl gene ENSG00000144406.
Subcellular location: Cell membrane
Subcellular location (Human Protein Atlas): Nuclear bodies; Vesicles
Pathways (Reactome):
Transport of small molecules: Stimuli-sensing channels
Gene Ontology:
Molecular function: monoatomic cation channel activity
Biological process: regulation of neuronal action potential; sodium ion transmembrane transport; monoatomic cation homeostasis
Cellular component: plasma membrane; voltage-gated sodium channel complex; axon; cation channel complex
Genetic constraint (gnomAD): Loss-of-function variants: 143 observed, 341.99 expected, observed/expected ratio (o/e) 0.42, 90% interval 0.36 to 0.48. The upper end of that interval is the gene's LOEUF score, 0.48, which puts it in group 2 of 6, group 1 being the genes least tolerant of losing a copy. Missense variants: 3,133 observed, 4,000.1 expected, observed/expected ratio (o/e) 0.78, 90% interval 0.76 to 0.81. Synonymous variants: 1,393 observed, 1,490.7 expected, observed/expected ratio (o/e) 0.93, 90% interval 0.89 to 0.98.
Gene-disease validity (ClinGen):
ClinGen rates the evidence that UNC80 causes each of these diseases.
hypotonia, infantile, with psychomotor retardation and characteristic facies 2 (autosomal recessive): Definitive.
Homologues: Orthologues: chimpanzee UNC80 (99% identical), dog UNC80 (98% identical), pig UNC80 (98% identical), macaque UNC80 (97% identical), mouse Unc80 (97% identical), rat Unc80 (96% identical), rabbit UNC80 (96% identical), guinea pig UNC80 (92% identical), zebrafish unc80 (76% identical), Drosophila melanogaster unc80 (30% identical), Caenorhabditis elegans unc-80 (28% identical).
Diseases named in the same sentence as UNC80 in open-access papers:
UNC80 is named in the same sentence as 27 diseases in open-access papers, as found by Europe PMC text mining. Sharing a sentence is not in itself a finding about the gene and the disease. The quoted sentences say what the papers report.
Intellectual disability (6 papers, 2020 to 2025). "Domains in UNC80, which are mutated in individuals with intellectual disability, interact to achieve the dendritic localization of NALCN complex." (PMID 32620897, 2020). "Additionally, mutations in Unc80 are associated with congenital infantile encephalopathy, intellectual disability, and growth issues." (PMID 40725218, 2025). "In particular, UNC80 mutants truncated at the C-terminal end retain the protein’s somatic function, but lack dendritic localization and cause severe intellectual disability, suggesting the importance for the proper regulation of dendritic resting membrane potential through the NALCN channel." (PMID 32620897, 2020). "Moreover, unc-80 mutations cause severe disorders such as hypotonia and intellectual disability." (PMID 38793790, 2024). "In humans, mutations in UNC80 are linked to profound neurological and cognitive issues, including hypotonia and severe intellectual disabilities, echoing the critical developmental role of Unc80 observed in mouse models." (PMID 38892173, 2024). "Pathogenic variants in UNC80 are associated with a severe neurodevelopmental disorder characterized by early-onset feeding difficulties, hypotonia, growth retardation, intellectual disability, and congenital encephalopathy, typically without structural brain malformations." (PMID 41458659, 2025). "In both humans and mice, individuals heterozygous for UNC80 null mutations develop normally, are fertile and do not have obvious abnormalities such as lethality and severe intellectual disability, suggesting that a reduction in UNC80 gene dosage by 50% is tolerated by the organisms." (PMID 32620897, 2020). "The human patients with similar C-terminal UNC80 truncations have basic motor skills, but lack fine motor coordination, do not have speech development, and have severe intellectual disability." (PMID 32620897, 2020).
developmental delays (4 papers, 2019 to 2025). "This study expands the understanding of UNC80 mutations by presenting two novel cases from a Yemeni family, demonstrating severe neurodevelopmental features, including developmental delays, hypotonia, and seizures, consistent with prior reports." (PMID 41458659, 2025). "Unc-80 mutations potentially cause a wide variety of neural disorders, including schizophrenia, Alzheimer’s disease, autism, and cognitive delay." (PMID 38793790, 2024). "UNC80 gene mutations have also been shown to cause global developmental delays, failure to thrive, and phenotypic dysmorphisms." (PMID 31223553, 2019). "Mutations in NALCN or UNC80 are related to a group of diseases named “NALCN channelopathies”, which are characterized by infantile hypotonia, psychomotor retardation, characteristic facies, congenital contractures of the limbs and face, and developmental delays." (PMID 35482723, 2022).
schizophrenia (3 papers, 2014 to 2024). A major psychotic disorder characterized by abnormalities in the perception or expression of reality. "In addition, genes encoding NALCN, NLF- 1, UNC-79, and UNC-80 proteins may be susceptibility loci for several diseases including bipolar disorder, schizophrenia, Alzheimer's disease, autism, epilepsy, alcoholism, cardiac diseases and cancer." (PMID 24904279, 2014).
alcoholism (1 paper, 2014). "In addition, two previous studies suggest the existence of a susceptibility locus located on chromosome 2, near the UNC-80 gene, linked to alcohol tolerance (markers D2S425, D2S434, D2S424, D2S1323, D2S1333) and the comorbidy of alcoholism and depression (marker DS1371) respectively." (PMID 24904279, 2014).
Dystonia (1 paper, 2021). An abnormally increased muscular tone that causes fixed abnormal postures. "The NALCN protein interacts with UNC80 and pathogenic variants in both genes have been associated to dystonia." (PMID 33557955, 2021).
kidney cancer (1 paper, 2024). Primary or metastatic malignant neoplasm involving the kidney. "A significant reduction in TMEM25 expression was observed among the mutation groups of BAP1, UNC80, EYS, SETD2 and XIRP, compared with the wild group, as BAP1 and SETD2 are commonly occurring mutation types in kidney cancer and have poor prognosis." (PMID 38189809, 2024).
microcephaly (1 paper, 2025). A congenital or acquired developmental disorder in which the circumference of the head is smaller than normal for the person's age and sex. "It is also noted that microcephaly is a critical trait in UNC80 mutations and can occur without any obvious brain deformities." (PMID 41458659, 2025).
neuroblastoma (1 paper, 2024). Neuroblastoma (NB) is the most common solid, extracranial childhood tumor. "Secondly, we transfected specific GFP-tagged wild-type Unc80 or Unc80S2732G encoding plasmids into a mouse neuroblastoma cell line (Neuro 2a cells) and performed immunofluorescence microscopy analyses to verify the localization of the fusion protein." (PMID 38892173, 2024).
pancreatic cancer (1 paper, 2024). "According to a bioinformatics study, unc-80 has been suggested to be a hub gene for pancreatic cancer." (PMID 38793790, 2024).
cancer (2 papers, 2014 to 2021). A tumor composed of atypical neoplastic, often pleomorphic cells that invade other tissues. "Variants in NALCN and UNC80 have been linked to many diseases, including several types of cancer." (PMID 33807947, 2021).
neurodevelopmental disorder (2 papers, 2021 to 2025). A behavioral and cognitive disorder with onset during the developmental period that involves impaired or aberrant development of intellectual, motor, or social functions. "In conclusion, the identification of three novel homozygous UNC80 mutations in this Yemeni family broadens our understanding of UNC80-related neurodevelopmental disorders and underscores the profound clinical impact of this gene on early development." (PMID 41458659, 2025). "Interest in the UNC79-UNC80-NALCN pathway has also risen, due to its essential role in the maintenance of respiration, the regulation of circadian rhythms, and because mutations of UNC80 and NALCN cause neurodevelopmental disorders, characterized by development delay and hypotonia." (PMID 33973519, 2021).
neurodegenerative disease (1 paper, 2024). A disorder of the central nervous system characterized by gradual and progressive loss of neural tissue and neurologic function. "For instance, issues such as mitochondrial dysfunction and neurodegenerative diseases, like ALS, are uniquely associated with UNC80 loss." (PMID 38892173, 2024).
UNC80 also shares sentences with these, for which no sentence is quoted: Alzheimer disease (2 papers); autism (2); tumor (2); autosomal recessive disease (1); bipolar disorder (1); brain disorder (1); cardiac diseases (1); channelopathies (1); epilepsy (1); Failure to thrive (1); growth failure (1); Hypotonia (1); Macrocephaly (1); Neurodevelopmental delay (1); non-small cell lung carcinoma (1).